IL10 (interleukin 10)
Diseases named in the same sentence as IL10 in open-access papers (continued):
Sharing a sentence is not in itself a finding about the gene and the disease.
tumor (continued). "The expression of inflammatory signaling molecules like TGF-β, indoleamine-2,3-dioxygenase (IDO), IL-10, and arginase by stromal cells and leukocytes within the tumor microenvironment contributes to the suppression of immune cell activity." (PMID 40001572, 2025). "Interleukin-10 (IL-10), which is produced primarily by macrophages, T cells, and tumor cells in CRLM, plays a crucial role in immune suppression." (PMID 41002563, 2025). "Our study is the first to report LPA-induced IL-10 production by tumor cells and identifies LPAR1-dependent upregulation of DR6 receptors in mediating this effect." (PMID 39187677, 2025). "TAMs predominantly exhibit an M2 phenotype within the tumor microenvironment, characterized by the secretion of anti-inflammatory cytokines (e.g., IL-10, TGF-β), expression of immune checkpoint molecules, and promotion of regulatory T cell (Treg) recruitment." (PMID 40406101, 2025). "They exert their regulatory function by secreting immunosuppressive cytokines, such as TGF-β and IL-10, which dampen the immune response within the tumor microenvironment (TME)." (PMID 39858472, 2025). "For instance, research has demonstrated that synthetic bacteria can enhance the anti-tumor immune response of NK cells by inhibiting neutrophil activity via IL-10 signaling while simultaneously activating CD8+ T cells." (PMID 41450920, 2025). "Mechanistically, APS co-administration enhanced CD8+ T-cell infiltration, increased splenic and thymic indices, modulated cytokine profiles (TNF-α, IL-2, IFN-γ, IL-12, IL-6, IL-10), and reduced PD-1/PD-L1 expression in tumor tissue." (PMID 41487528, 2025). "Its increased levels were associated with an immunosuppressive tumor microenvironment, as PSG1 upregulates cytokines such as IL-10 and TGF-β, which can facilitate immune escape." (PMID 40806565, 2025). "They mitigate anti-tumor immune responses through numerous immunosuppressive mechanisms, including secretion of immunosuppressive cytokines such as IL-10 and IL-35." (PMID 40908470, 2025). "The interaction between these 2 cell types leads to T-cell dysfunction and promotes the secretion of IL-10, which, in turn, facilitates tumor growth." (PMID 41367015, 2025). "It is often described as a “double-edged sword” because while IL-10 can limit chronic inflammation, potentially suppressing tumor initiation, in established cancers, IL-10 frequently contributes to immune evasion by the tumor." (PMID 41007766, 2025). "In particular, glycoconjugates and receptor-specific antibodies targeting DC-SIGN-mediated IL-10 secretion offer distinct advantages to developing immune modulators or tumor vaccines." (PMID 40076949, 2025). "MDSCs are believed to play significant roles in tumor survival and metastasis through various mechanisms, including the induction of Tregs, production of interleukin-10 (IL-10), and modulation of NK cells." (PMID 41567188, 2025). "This crosstalk results in increased production of IL-10 by MDSCs, while reducing the secretion of tumor-antagonizing IL-12 by TAMs." (PMID 40169560, 2025). "Known for its anti-inflammatory effects, IL-10 suppresses pro-inflammatory cytokine production and enhances regulatory T cell (Treg) development, thereby dampening anti-tumor immune responses." (PMID 40563651, 2025). "IL-10, as an immunosuppressive cytokine, can impede the anti-tumor immune response, facilitate tumor immune evasion, and hence expedite tumor development." (PMID 40370720, 2025). "Tumor cells can secrete immunosuppressive cytokines such as transforming growth factor- β (TGF- β) and interleukin-10 (IL-10), which can inhibit the activation of cytotoxic immune cells and promote the formation of an immunotolerant tumor microenvironment." (PMID 40276499, 2025). "Classical activated macrophages (M1 macrophages) typically inhibit tumor growth, while M2 macrophages promote tumor cell growth, invasion, and metastasis by secreting IL-10, TGF-β, and MMPs." (PMID 40260293, 2025).
tumor (continued). "Pro-tumorigenic cytokines include IL-6, TGF-β, vascular endothelial growth factor (VEGF), and IL-10, while anti-tumor cytokines include IFN-γ, tumor necrosis factor-α (TNF-α), and IL-12." (PMID 40227644, 2025). "On the other hand, Tregs create an immunosuppressive microenvironment by inhibiting T cell activation and secreting TGF-β and interleukin-10 (IL-10), which promote tumor evasion of immunosurveillance." (PMID 40534854, 2025). "ONA also interfered with the cell-cell interactions that enhance TAMs’ protumor functions, reducing the secretion of M2 macrophage markers like IL-10 and other tumor-promoting cytokines." (PMID 40330466, 2025). "This shift is characterized by the up-regulation of pro-inflammatory cytokines such as IL-6 and TNF-α, which have anti-tumor properties, and the down-regulation of immunosuppressive cytokines such as IL-10 and TGF-β." (PMID 40507156, 2025). "Meanwhile, Parabacteroides distasonis has been reported to stimulate the IL‐10 production in Tregs, potentially contributing to immune suppression in the tumor microenvironment." (PMID 40685922, 2025). "The M2-type TAMs are induced by IL-4 and IL-10, which display both anti-inflammatory and pro-tumor functions." (PMID 40709184, 2025). "In solid tumor, it has beenhypothesized that IL-10 creates an immunosuppressive microenvironment conduciveto tumor progression, potentially by interacting directly with cancer cells topromote cellular proliferation." (PMID 40026520, 2025). "They report that both IL-6 and IL-10 were expressed on TAMs and tumour cells, and that their signalling is critical for disease progression and early relapse in OC patients." (PMID 41463341, 2025). "In contrast, M2 macrophages, which are abundant in the TME of GBM, facilitate tumor growth by secreting anti-inflammatory cytokines (e.g., IL-10 and TGF-β), promoting angiogenesis, and remodeling the extracellular matrix." (PMID 41164132, 2025). "Specifically, recent studies have demonstrated that KLRG1+ ILC2s can acquire anti-tumor functions through IL-10 production and IL-33–mediated activation." (PMID 40497988, 2025). "M2-like TAMs then contribute to tumor progression by secreting anti-inflammatory cytokines (IL-10, TGF-β), promoting angiogenesis, and expressing immune checkpoint ligands such as PD-L1." (PMID 40948759, 2025). "These M2-like TAMs play a critical role in cancer metastatic progression by promoting tumor survival, angiogenesis, immune suppression, and metastasis through the secretion of factors like IL-10, TGF-β, and VEGF." (PMID 40330466, 2025). "Conversely, dysregulation of anti-inflammatory cytokines such as IL-10 impairs immune surveillance and facilitates tumor growth." (PMID 41303495, 2025). "In various solid tumors, such as ovarian, colorectal, and pancreatic cancers, aberrant activation of the MyD88 pathway in tumor-infiltrating myeloid cells leads to excessive production of immunosuppressive cytokines like IL-10 and TGF-β." (PMID 41488647, 2025). "In immune cells, STAT3 signaling encourages autocrine production of IL-6 that sustains tumor-promoting inflammation along with immunosuppressive factors such as IL-10 and TGFβ which blunt the anti-tumor response." (PMID 40356899, 2025). "They enable therapeutic delivery of saporin and IL‐10, inhibiting tumor growth and enhancing T cell activity, showcasing potential for protein therapeutic applications in disease treatment." (PMID 40056044, 2025). "Subsequently, TAMs suppress cytotoxic T cell responses through the production of Arg1, programmed death-ligand 1 (PD-L1), and IL-10, allowing tumors to evade anti-tumor immunity." (PMID 41236793, 2025). "TAMs are typically polarized toward an M2 phenotype, supporting tumor growth and immunosuppression through the secretion of pro-tumorigenic cytokines such as IL-10, TGF-β, and IL-6." (PMID 39833954, 2025). "As a pivotal mediator of anti-inflammatory responses, IL-10 cytokine is primarily produced by tumor cells and leukocytes." (PMID 40563367, 2025).
tumor (continued). "While tumor cells release IL-10, they stimulate IL-10 production in lymphocytes via a PGE2-mediated mechanism." (PMID 41179937, 2025). "These macrophages are skewed toward an M2-like phenotype under the influence of ROS, promoting tumor progression and immunosuppression by secreting anti-inflammatory cytokines such as interleukin-10 (IL-10) and TGF-β." (PMID 39857427, 2025). "IL-24 is a member of the IL-10 cytokine family with both pro- and anti-inflammatory roles and roles in tumor suppression." (PMID 41301428, 2025). "By contrast, Th2 cells support humoral responses via IL-4, IL-10, and IL-13, suppressing Th1-mediated responses and fostering an immunosuppressive tumor microenvironment." (PMID 41176307, 2025). "Histone lactylation acidification participates in PERK-driven glucose metabolism and ATF4-regulated GLUT1 expression, regulates mononuclear cell-derived macrophage IL-10 expression, changes immunosuppressive activity, and promotes tumor progression." (PMID 41041328, 2025). "MAFs are known to secrete immunosuppressive cytokines, such as IL-10, and promote tumor growth by inducing neutrophil extracellular traps (NETs), which contribute to T cell exhaustion." (PMID 40872475, 2025). "Constitutive STAT3 activation in tumor cells is a well-established driver of immunosuppression, promoting IL-10 production and Th2/M2 skewing in the microenvironment." (PMID 41403933, 2025). "Several studies identified proteins such as Cyfra 21-1, Cathepsin B, AKR1B10, IL-10, IL-13, and TNF-α as being associated with tumor burden, histological grade, or recurrence risk." (PMID 41149126, 2025). "Although IL-10–based therapies exhibit anti-tumor potential and good tolerability, their clinical efficacy remains modest, underscoring the need for optimized delivery methods and combinatorial approaches in TNBC." (PMID 40868199, 2025). "The shift toward a Th2 response leads to increased levels of IL-4 and IL-10, weakening the cellular immune response needed to combat intracellular pathogens and tumor cells." (PMID 39857306, 2025). "They express immunosuppressive FCRL4, cytokine IL-10 and receptors, typically participating in the inhibition of anti-tumor response." (PMID 39744696, 2025). "M2 TAMs promote tumor progression by releasing IL-10 and TGF-β, which further suppress T-cell-mediated anti-tumor immunity." (PMID 40312353, 2025). "Neutrophils, in turn, promote chronic inflammation and play a key role in tumor progression and metastasis by secreting IL-10, which suppresses the function of cytotoxic T cells and inhibits NK cells, leading to resistance." (PMID 41440517, 2025). "MSC2: Secretion of CCL5, TGF‐β, IL‐6, VEGF, IL‐8, IL‐10, MMPs (Induction of angiogenesis, metastasis, enhanced tumor stemness, immunosuppression, differentiation into CAF)." (PMID 40150879, 2025). "For instance, IL-6 promotes tumor cell proliferation and angiogenesis; IL-10 exerts immunosuppressive effects that favor viral persistence; IL-12 enhances Th1-mediated antitumor immunity; and IL-17 is involved in chronic inflammation and tumor promotion." (PMID 41408300, 2025). "In contrast, such extracellular release of the anti-inflammatory cytokine IL-10 decreased in cocultures containing tumor cells treated with NanoTAC (+L)." (PMID 40998785, 2025). "They observed that IL-10 producing CD19+ Bregs can suppress anti-tumor immunity, promoting tumor progression." (PMID 40177538, 2025). "TGF-β and IL-10 contribute to the immunosuppressive tumor microenvironment by inhibiting effector lymphocyte functions and promoting regulatory T-cell activity, further suppressing immune responses against the tumor." (PMID 41394861, 2025). "The following experiment revealed that sGRP78 bound with tumor‐infiltrating B cells, converting the latter into IL‐10+/PD‐L1+ ones, thereby promoting Treg formation and suppressing T cell‐mediated antitumor cytotoxicity." (PMID 40936109, 2025).
tumor (continued). "Tumour-educated TAMs can then secrete IL-10, TGF-β, and regulatory T-cell (Treg)-attracting chemokines such as CCL22, further promoting immunosuppression in the adaptive compartment." (PMID 41309950, 2025). "Pegilodecakin (PEGylated recombinant IL‐10) induces the proliferation of CD8 T cells both within the tumor microenvironment and in the systemic circulation, while also activating CD8 T cells within TME." (PMID 39791593, 2025). "These M2 macrophages secrete immunosuppressive cytokines (e.g., IL-10), promote angiogenesis, and facilitate tissue remodeling, all of which contribute to tumor progression and the expansion of Tregs." (PMID 40281554, 2025). "On the other hand, specific B cell subsets exert immunosuppressive effects by secreting IL-10 or upregulating PD-L1, thereby promoting tumor growth." (PMID 41246318, 2025). "SCFAs have bifunctional utility: reducing the secretion of IL-10, an anti-inflammatory cytokine that promotes tumor cell proliferation via immunosuppression, while also increasing NK extracellular vesicle secretion of IFNγ that aids in tumor-killing." (PMID 40422211, 2025). "In the TME, Treg cells suppress the immune response and promote tumor immune escape by secreting cytokines such as IL-10 and TGF-β." (PMID 41035634, 2025). "This polarization of M2 macrophages promotes the formation of an immunosuppressive environment and promotes tumor immune escape, Here, miR-155 does this by down-regulating SHIP1 and increasing the secretion of M2-associated cytokines such as IL-10 and TGF-β." (PMID 40625740, 2025). "A study of HBV-associated liver cancer showed that CCR4+ Treg were predominantly infiltrated in HBV+ tumor tissue, which expressed IL-10 and IL-35 more than CCR4− Treg and was more potent at suppressing CD8+ T-cells, which led to resistance to sorafenib." (PMID 41226585, 2025). "In lung cancer, CAFs derived from freshly resected tissue have been shown to secrete immunosuppressive cytokines such as IL-6, TGF-β, and IL-10, which contribute to the immune suppression observed in the tumor microenvironment." (PMID 40453074, 2025). "Tumor-derived suppressive cytokines such as IL-10, and TGF-β, as well as hypoxic conditions, inhibit CD103+ DC differentiation and antigen-presenting capacity." (PMID 40909271, 2025). "Within the tumor microenvironment, factors such as hypoxia and immunosuppressive cytokines (e.g., IL-10, TGF-β) skew TAMs toward an M2 phenotype and suppress phagocytic function." (PMID 40724825, 2025). "Mechanistically, TSLP derived from cervical cancer cells up-regulated the levels of anti-inflammatory cytokines (IL-10, IL-4, IL-5 and IL-13) in eosinophils, which in turn promoted the proliferation and restricted the apoptosis of tumor cells." (PMID 40050933, 2025). "In contrast, M2 macrophages suppress inflammation by releasing cytokines, promote immune suppression (such as IL-10, IL-13), facilitate tumor cell metastasis through factors like EGF and MMP, and also promote angiogenesis." (PMID 40704062, 2025). "Conversely, immunosuppressive T regulatory cells, such as CD4+ T cells that secrete TGF-β and IL-10, facilitate tumor development." (PMID 40219336, 2025). "The decrease in IL-10 levels in the Triple therapy group indicates a suppression of immunosuppressive pathways, thereby boosting anti-tumor immunity." (PMID 40403026, 2025). "A recent study by Zotta and colleagues provides new insights into the role of mitochondrial complex III (CIII) in regulating the anti-inflammatory cytokine interleukin-10 (IL-10) and its implications for tumor immunity." (PMID 40620536, 2025). "IL-10 is produced by human tumor cells and, in gastric cancer, contributes to the establishment of an immunosuppressive microenvironment that favors tumor growth." (PMID 41011273, 2025).
tumor (continued). "This shift was associated with decreased pro-inflammatory cytokines (IL-1β, TNF-α) and increased anti-inflammatory cytokines (IL-10, IL-4), along with suppression of tumor-promoting pathways and improved intestinal barrier integrity." (PMID 40417220, 2025). "Among the evaluated cytokines in the early stage of MC4-L2 tumors, only a rise in IL-10 expression was detected; after tumor progression, IL-13 and IL-22 were overexpressed in addition to IL-10." (PMID 39877637, 2025). "When profiling the tumor microenvironment, the decreased infiltration of Treg, downregulation of IL‐10 and PD‐L1 in B cells were observed as expected." (PMID 40936109, 2025). "M2d macrophages, recently identified as tumor-associated macrophages, are induced by TLR ligands or IL-6 and secrete IL-10 and vascular endothelial growth factor (VEGF), promoting tumor vessel formation and metastasis." (PMID 40760449, 2025). "Tregs inhibit the activation and proliferation of effector T cells, thereby reducing anti-tumor immune responses, while MDSCs suppress immunity through the production of inhibitory cytokines like IL-10 and TGF-β." (PMID 39897423, 2025). "The results confirmed that IL8 and IL10 increased the protein levels of ITGβ8 in A549 cells, which indicates an interaction between macrophages and tumor cells." (PMID 39535362, 2025). "The interaction between MDSCs and macrophages requires direct cell-to-cell contact; moreover, IL-10 produced by MDSCs inhibits IL-12 production by macrophages, skewing them toward a type II tumor-promoting phenotype." (PMID 41368628, 2025). "Tumor cells, in their efforts to evade the immune response, can secrete interleukins such as IL-10 and TGF-β, which act as potent inhibitors of NK cell proliferation and effectiveness." (PMID 40299429, 2025). "For example, tumor-derived IL-10 and TGF-β drive DCs into a tolerogenic state, reducing MHC-II and co-stimulatory molecule expression while upregulating inhibitory ligands (e.g. PD-L1), which together impair effector T cell priming." (PMID 41488634, 2025). "IL-10 has potent anti-inflammatory properties and protects against tissue damage in allergic diseases, autoimmune disorders, organ transplantation, and tumor tolerance." (PMID 40861439, 2025). "This unique anti-tumor multifunctionality positions IL-10 as a compelling candidate for next-generation cancer immunotherapy, particularly in combination regimens with immune checkpoint inhibitors or other immunomodulatory agents." (PMID 40149345, 2025). "In contrast, M2-type TAMs contribute to tumor progression by secreting immunosuppressive factors, including IL-10 and TGF-β." (PMID 41394878, 2025). "Studies have shown that CD8+CD14+ T-cells accumulate in liver allografts and during hepatic viral and tumor-specific responses in a mouse model, producing IL-10 and IL-2 ex vivo." (PMID 41148820, 2025). "Cells from animals treated with inactive OpdA showed a significant increase in IL-10 secretion upon stimulation with tumor antigens." (PMID 41019059, 2025). "Yet, restoring their expression decreased tumor cell viability and T cell exhaustion by targeting tumor PD-L1, thereby reducing IL-10 and boosting IL-2/IFN-γ." (PMID 40647470, 2025). "Increased regulatory T cells (Tregs) in IAC samples suggested an immunosuppressive trend during tumor progression, potentially regulated by cytokines such as interleukin-6 (IL-6), interleukin-10 (IL-10), and tumor necrosis factor-alpha (TNF-α)." (PMID 41417416, 2025). "Simultaneously, their secretion of TNF-α and IL-10 promotes regulatory T (Treg) cell-mediated immune tolerance, weakening anti-tumor immune responses and enhancing tumor progression." (PMID 40299416, 2025). "Tumor-derived cytokines such as IL-6, IL-8, IL-10, CSF-1, CCL2, CXCL2, PGE2 and TGF-β promote MDSC expansion and recruitment, whereas hypoxia shifts MDSC metabolism toward fatty acid oxidation, reinforcing their immunosuppressive properties." (PMID 40628732, 2025).